GRIA2 (glutamate ionotropic receptor AMPA type subunit 2)
Diseases named in the same sentence as GRIA2 in open-access papers (continued):
Sharing a sentence is not in itself a finding about the gene and the disease.
neurodevelopmental disorder (17 papers, 2018 to 2024). A behavioral and cognitive disorder with onset during the developmental period that involves impaired or aberrant development of intellectual, motor, or social functions. "Putative loss-of-function variants in the human GluA2 (GRIA2) gene have been associated with several neurodevelopmental disorders." (PMID 38410160, 2024). "This is the third study on the GRIA2 variant associated with neurodevelopmental disorders, and our study expands the spectrum of phenotypic variations of GRIA2." (PMID 36329391, 2022). "The GRIA2 gene is a excitatory neurotransmitter associated with various neurodevelopmental disorders in humans." (PMID 37489751, 2022). "In summary, patients with GRIA2 pathogenetic variants display a broad spectrum of neurodevelopmental disorders, which makes it difficult for the clinical geneticist to address a specific test." (PMID 34768579, 2021). "It is highly likely that dysregulation of a number of transcriptional and post-transcriptional modulations is implicated in the GRIA2 neurodevelopmental disorders." (PMID 31300657, 2019). "Our results show that de-novo variants in GRIA2 can cause neurodevelopmental disorders, complementing evidence that other genetic causes of ID, ASD and DEE also disrupt glutamatergic synaptic transmission." (PMID 31300657, 2019). "GRIA2 mutations are also associated with neurodevelopmental disorders." (PMID 37041519, 2023). "In support of this, a recent study has identified several patients with neurodevelopmental disorders including DEE all of which displayed de novo mutations in GRIA2 including one patient with a mutation in the Q/R editing site who displayed a seizure phenotype." (PMID 37759260, 2023). "Few reports have described an association between GRIA2 variants and neurodevelopmental disorders." (PMID 34768579, 2021). "On June 18, 2020, neurodevelopmental disorder with language impairment and behavioral abnormalities (OMIM 618917) caused by the GRIA2 variant was registered as a new entry." (PMID 35346031, 2022). "GRIA2 (glutamate receptor, ionotropic AMPA 2): 2/24 patients (8%) with neurodevelopmental disorder and EE had neonatal-onset seizures and MD." (PMID 33919646, 2021). "Also, we have identified 15 de novo variants in genes that were previously implicated in ASD or related neurodevelopmental disorders (PHF21A, WASF1, TCF20, DEAF1, MED13, CREBBP, KDM6B,SMURF1, ADNP, CACNA1G, MYT1L, KIF13B, GRIA2, CHM, and KCNK9)." (PMID 38572415, 2024).
neurological disorders (15 papers, 2014 to 2025). "The downregulated genes include one encoding a protein that interacts with amyloid-β precursor protein (ANKS1B) and two encoding glutamate receptors (GRIA2, GRM3), suggesting changes in astrocytic responses to synaptic glutamate release in multiple neurological disorders." (PMID 34172753, 2021). "Moreover, editing events of these genes have been associated with cancer progression (e.g., AZIN1, COPA, CCNI, and FLNB) or neurological disorders (e.g., GRIK2 and GRIA2–4)." (PMID 35406793, 2022).
cancer (13 papers, 2014 to 2026). A tumor composed of atypical neoplastic, often pleomorphic cells that invade other tissues. "Single-cell RNA sequencing revealed that cancer-associated fibroblasts are the primary source of glutamate in the peritoneal microenvironment, which establishes a paracrine axis that enhances GRIA2-driven metastasis." (PMID 41806318, 2026). "It exhibits up-regulated expressions of the cancer-associated lncRNAs FOXCUT, SAMMSON, ENSG00000251320, and ENSG00000248927, as well as ion channels in nerve fibers, such as GRIA2 and GABARR1." (PMID 37445678, 2023). "Although specific studies directly linking GRIA2 to PC are limited, exploring its expression patterns and functional relevance in cancer cells could provide valuable insights into its potential as a biomarker or therapeutic target." (PMID 40641572, 2025). "GRIA2, through its role in regulating calcium influx and downstream signaling pathways, could potentially affect cellular processes relevant to cancer biology, such as proliferation, apoptosis, and migration." (PMID 40641572, 2025). "There are conflicting reports of Gria2 gene function in cancer biology." (PMID 35263365, 2022). "In the case of GRIA2, there are conflicting reports regarding its role in cancer biology." (PMID 25326682, 2014). "Therefore, despite the limitations, we assume that the results of our study on DNA methylation of apoptosis-associated genes suggest the possible involvement of five genes (SETDB1, TWIST1, HDAC1, SP1, and GRIA2) in the phenomenon of inverse comorbidity of neurodegenerative diseases and cancers." (PMID 40843670, 2025). "A recent pan-cancer study identified an appreciable number of RNA editing sites with potential clinical implications (AZIN1, COG3, and GRIA2)." (PMID 30760294, 2019). "Furthermore, by resorting to several recent review articles, there were 26 RESs with cancer‐related clinical significance that were covered by our dataset, which resided in 7 genes (AZIN1, BLCAP, COG3, COPA, FLNB, GRIA2, and NEIL1)." (PMID 34319007, 2021).
infection (7 papers, 2012 to 2025). The state of being infected such as from the introduction of a foreign agent such as serum, vaccine, antigenic substance or organism. "The infection led to a significant downregulation of the Gria2 gene expression to about 0.13-fold, but there was significant improvement after JRLE treatment, recording an upregulation of 0.79-fold compared to the chloroquine group (0.91-fold)." (PMID 40260212, 2025). "The proliferation rate of ISK cells was inhibited after infection with GRIA2 shRNA." (PMID 32201522, 2020).
psychiatric disorder (7 papers, 2015 to 2024). A disorder characterized by behavioral and/or psychological abnormalities, often accompanied by physical symptoms. "Focusing on miR-223, we then examined the expression of proven miR-223 targets, GRIA2 and GRIN2B, which are of relevance to psychiatric disorders, in our cohort using qRT-PCR with normalization to the unaltered and reliable for postmortem studies 18S rRNA." (PMID 31775160, 2020).
brain diseases (2 papers, 2022 to 2024). "Apart from the connection of RNA editing at the Gria2-encoded subunit of the AMPA glutamate receptor with several brain disorders, the GluK1 and GluK2 subunits of kainite receptors (KA) also possess the Q/R RNA editing site, which also affects Ca++ permeability." (PMID 35327657, 2022). "Given the prominent role of this recoding event, it is not surprising that Gria2 was selected as a study target in the context of several brain disorders, including HD, AD, ALS, SCZ and has been detected as under-edited in these disease conditions." (PMID 35327657, 2022).
GRIA2 also shares sentences with these, for which no sentence is quoted: ischemia (13 papers); cognitive deficits (12); autism spectrum disorder (7); Stroke (7); Hyperammonemia (6); neurodegenerative disease (6); autism (5); developmental epileptic encephalopathy (5); memory impairment (5); astrocytoma (4); brain ischemia (4); encephalitis (4); Epileptic encephalopathy (4); cocaine addiction (3); developmental delay (3); epileptic seizures (3); glaucoma (3); ischemic stroke (3); amnesia (2); Cerebral ischemia (2); dementia (2); fragile X syndrome (2); Hypoglycemia (2); injury (2); Neurodevelopmental delay (2); neuropathic pain (2); retinal degeneration (2); Spasticity (2); sporadic amyotrophic lateral sclerosis (2); temporal lobe epilepsy (2).
A further 48 diseases each share a sentence with GRIA2 in 2 papers or fewer.